MTOR (mechanistic target of rapamycin kinase)
Diseases named in the same sentence as MTOR in open-access papers (continued):
Sharing a sentence is not in itself a finding about the gene and the disease.
sarcoidosis (continued). "Dysfunction of mTOR in sarcoidosis has been highlighted by genetic screening of familial forms of the disease." (PMID 34440765, 2021). "Our previous data on a subset of five sarcoidosis families suggested that genetic defects in Rac1, mTOR, and autophagy-related pathways are relevant factors in familial predisposition to sarcoidosis." (PMID 34440765, 2021). "The choice to specifically study MD-macrophages in these patients was supported by recent works showing that in vitro models of granuloma using PBMCs can mimic sarcoidosis events such as phagosome-regulated mTOR or IL-13 signaling." (PMID 34456926, 2021). "In terms of clinical relevance, successful treatment of a sarcoidosis patient with the mTOR inhibitor rapamycin has been reported." (PMID 32760396, 2020). "It should also be noted that successful treatment of a sarcoidosis patient with the mTOR inhibitor rapamycin has previously been reported." (PMID 31681260, 2019). "The key works used to search were [sarcoidosis + sirolimus] and] sarcoidosis + mTOR]." (PMID 40996589, 2025). "Similar to how mTOR inhibitors have risen to efficacy against sarcoidosis, the identification of these molecular dysregulations facilitates the future use of drugs inhibiting these pathways, leading to a reduction in granulomatous inflammation and progression of the disease." (PMID 40078389, 2025). "mTOR pathway plays an important role in pathogenesis of sarcoidosis." (PMID 39904950, 2025). "mTOR was recently investigated in sarcoidosis, however with contrasting results." (PMID 37445947, 2023). "As a future direction, we plan to investigate interactions between HIF and other signaling pathways identified in the pathogenesis of sarcoidosis as mTOR, NLRP3 inflammasome, JAK/STAT, or heat shock proteins, already known to interfere with the HIF/hypoxia pathway." (PMID 34456926, 2021). "Thus, mTOR inhibitors, such as sirolimus, should be further investigated as a potential therapy option for sarcoidosis." (PMID 33036432, 2020). "However, the molecular mechanisms underpinning mTOR involvement in human sarcoidosis remain to be elucidated." (PMID 31681260, 2019). "Interestingly, a link between mTOR and autophagy was recently proposed in familial cases of sarcoidosis." (PMID 31681260, 2019). "Its clinical presentation, with predominant (90%) thoracic involvement, histopathological appearance and supposed underlying biology (involving the mTOR pathway in immune cells, Th17 polarization and TReg dysfunction) are indistinguishable from those of sarcoidosis." (PMID 35740604, 2022). "Interestingly, whole exome sequencing (WES) suggested that the mTOR signaling pathway could be involved in the development of familial sarcoidosis." (PMID 32760396, 2020). "Thus, ILK-mediated mTOR activation could be a possible mechanism mediating inflammation in a subset of sarcoidosis cases." (PMID 32764642, 2020). "In two families with a severe form of sarcoidosis, we demonstrated deleterious mutations in DDIT4 (DNA damage inducible transcript 4 gene), also called Rtp801, encoding a factor that turns off the metabolic activity triggered by mTOR by stabilizing the TSC1–TSC2 inhibitory complex." (PMID 32823753, 2020). "Our group recently identified the mechanistic target of rapamycin (mTOR) complex 1 (mTORC1) signaling pathway as a molecular mechanism in the initiation and maintenance of granulomas in mice, as well as its activation in sarcoidosis patients suffering from a progressive form of the disease." (PMID 31681260, 2019). "Therefore, the role of mTOR in these diseases may in fact be manifold, and the connection between mTOR and autophagy in both tuberculosis and sarcoidosis suggests that this could be a key molecular pathway in the pathogenesis of granulomatous diseases." (PMID 31681260, 2019).
sarcoidosis (continued). "Recent studies have found that the pathological mechanisms of sarcoidosis also involve other pro-inflammatory factors (such as TNF-α) and multiple signaling pathways (such as mTOR and JAK-STAT pathway)." (PMID 39904950, 2025). "Few case reports showed the efficacy of mTOR inhibitor sirolimus in the treatment of GLILD, suggesting a possible role of mTOR pathway in GLILD as shown for sarcoidosis." (PMID 39431514, 2024). "More specifically, the blockade of PD-1 in sarcoidosis induces a restoration of correct T cell proliferation and the normal expression of PI3K/AKT/mTOR signaling." (PMID 37445947, 2023). "Altogether, granulomatosis induced by ICIs and real sarcoidosis not only share clinical and pathology criteria, but they also have common biological mechanisms involving Th1 and Th17 and possibly the PI3K/mTOR pathway in macrophages and T cells." (PMID 35740604, 2022). "Besides mTOR, JAK/STAT and Rac1 pathway, NLRP3 pathway is another important pathway activated in granuloma formation of sarcoidosis." (PMID 39904950, 2025). "Recent results have shown the effectiveness of mTOR inhibitors and JAK inhibitors in sarcoidosis." (PMID 40002701, 2025). "High expression of mTOR signaling in granulomatous lesions is not predictive for the clinical course of sarcoidosis." (PMID 39382646, 2024). "We speculate that the dysregulation of the pathway involving mTOR and MAPK and their interaction might play a role in the pathogenesis of other diseases, including sarcoidosis." (PMID 28754097, 2017). "While these findings are significant—particularly given the role of mTOR and autophagy in the pathogenesis of sarcoidosis— available genome-wide association studies (GWAS) have not identified TSC2 mutations as a risk factor for sarcoidosis." (PMID 39996765, 2025). "Furthermore, mTOR signalling was detected in CD68 + macrophages in 78% of hearts from SCD victims diagnosed with CS postmortem, indicating involvement of the mTOR pathway in the pathogenesis of several forms of sarcoidosis." (PMID 40996589, 2025). "Specifically, early T effector cells (ETE) from sarcoidosis patients had significant downregulation of TCR signaling (labeled “SLE T cell signaling pathway” here) and ICOS-ICOSL signaling, as well as PI3K/AKT, ERK/MAPK, NFAT, ERBB2 (TOB), sirtuin, and mTOR signaling, relative to controls." (PMID 33363531, 2020). "Moreover, estrogens have been shown to activate the mechanistic target of rapamycin (mTOR) and phosphatidylinositol 3-kinase (PI3K) pathways, and recent research has suggested that these pathways may play a role in the development and progression of sarcoidosis." (PMID 38212490, 2024).
inflammatory bowel disease (30 papers, 2015 to 2025). A spectrum of small and large bowel inflammatory diseases of unknown etiology. "In the context of inflammatory bowel disease, dagliflozin has been observed to diminish mammalian target of rapamycin (mTOR) levels by enhancing AMPK phosphorylation." (PMID 39963239, 2025). "For example, PAR2 activation was proven to increase intestinal wall thickness, granulocyte infiltration and bacterial translocation through the PAR2/Akt/mTOR pathway in inflammatory bowel disease (IBD)." (PMID 39301020, 2024). "Activation of the mTOR signaling pathway in intestinal epithelial cells induces events leading to inflammatory bowel diseases." (PMID 38276311, 2024). "By analyzing 52 DEmiRs using the KEGG database, 104 pathways, such as Fc gamma R-mediated phagocytosis, Inflammatory bowel disease IBD, mTOR signaling pathway, were shown to be considerably enriched." (PMID 38037065, 2023). "Furthermore, it has been implicated that epithelial mTOR hyperactivation was a vicious circuit in the pathogenesis of inflammatory bowel diseases (IBD) and cancer." (PMID 36465179, 2022). "These genes are mainly involved in the cytokine-cytokine receptor interaction, inflammatory bowel disease and several signaling pathways, including mTOR signaling pathway." (PMID 36371321, 2022). "MTOR inhibitors are immunosuppressive agents that range in their clinical indications from inflammatory bowel disease to dermatological disease and transplant rejection." (PMID 33919596, 2021). "A study of inflammatory bowel disease (IBD) found that tryptase promotes fibrosis by activating the PAR-2/Akt/mTOR pathway of fibroblasts." (PMID 34203383, 2021). "Together, our findings revealed that neddylation inhibition suppressed DC functions through mTOR signaling pathway and provided a potential therapeutic opportunity in inflammatory bowel diseases." (PMID 27224922, 2016). "Notably, IFN-γ mediates Paneth cell death by inhibiting mTOR, a mechanism resembling that in human inflammatory bowel diseases such as Crohn’s disease." (PMID 40266920, 2025). "In addition, MC tryptase was shown to promote inflammatory bowel disease-induced intestinal fibrosis through the PAR-2/Akt/mammalian target of the rapamycin (mTOR) pathway of fibroblasts." (PMID 39355120, 2024). "mTOR signaling has been shown to play an important role in inflammatory bowel disease." (PMID 32290362, 2020). "The finding that mTOR is also important for T-cell accumulation in the intestines suggests that mTOR inhibition can also be a potential therapeutic strategy to treat intestinal diseases, such as inflammatory bowel diseases, in which T-cells play an important role." (PMID 27731345, 2016). "In another example, the clinically approved drug metformin has been shown to activate AMPK and suppress mTOR signaling, thereby reducing Th17-driven inflammation while enhancing Treg differentiation in models of inflammatory bowel disease (IBD)." (PMID 40957982, 2025). "Naser-Aldin Lashgari and his team collected data from clinical sources, and the results showed that inhibition of the mTOR signaling pathway reduces inflammation and cytokines in inflammatory bowel disease (IBD)." (PMID 37498338, 2023). "Indeed, mTOR appears to be involved in many conditions characterized by chronic inflammation (the manifestation of dysregulated immune reactivity) and is, for example, elevated in human inflammatory bowel disease (IBD)." (PMID 26180685, 2015). "The Kyoto Encyclopedia of Genes and Genomes (KEGG) pathway was enriched mainly in the mTOR signaling pathway, TNF signaling pathway, Jak-STAT signaling pathway and inflammatory bowel disease." (PMID 39809743, 2025). "Resveratrol also protected inflammatory bowel disease and improved gut barrier function by downregulating the expression of HIF-1, mTOR, and STAT3 pathway." (PMID 32973502, 2020).
injury (30 papers, 2016 to 2026). Damage inflicted on the body as the direct or indirect result of an external force, with or without disruption of structural continuity. "Our data also suggested that the PI3K/AKT/mTOR-mediated mechanisms were the prominent pathways involved in the protective effects of G-Re on TAA-induced liver injury." (PMID 40620672, 2025). "Studies have confirmed that Acetovanillone can activate the PI3K/Akt/mTOR/NRF2 pathway thereby preventing cyclophosphamide-induced acute lung injury." (PMID 39670103, 2024). "Taraxacum mongolicum extract reduced the inflammatory response in the lung by regulating the PI3K/Akt/mTOR axis activity in LPS-induced acute lung injury in mice." (PMID 36235741, 2022). "Metformin decreases the inflammatory response by restoring AMP-activated protein kinase (AMPK)-dependent suppression of mTOR in endotoxemia-induced inflammatory lung injury." (PMID 36235741, 2022). "Rapamycin inhibits the activation of NOD-like receptor protein 3 (NLRP3) by regulating the mammalian target of rapamycin (mTOR) to treat obstructive sleep apnea-related renal injury." (PMID 35184679, 2022). "Another study also revealed that melatonin activates an Akt/mTOR-dependent pathway to induce HO-1 expression, which prevents hemorrhagic shock-induced liver injury." (PMID 34194603, 2021). "Some studies suggest that the role of mTOR is associated with cell death and neuronal protection, whereas others report post-traumatic brain injury and that mTOR signaling may promote neuroregeneration." (PMID 35794772, 2023). "Therefore, this study aims to investigate the effect of ST on hepatic oxidative injury, inflammation, apoptosis, and the mTOR/NF-κB/NLRP3 signaling pathway in streptozotocin (STZ)-induced liver injury." (PMID 38131990, 2023). "Likewise, glycyrrhizic acid was shown to inhibit the production of inflammatory factors in LPS-induced acute lung injury in mice by regulating autophagy related to the PI3K/Akt/mTOR pathway." (PMID 36235741, 2022). "However, it is unclarified whether the mTOR pathway is involved in hyperoxic acute lung injury (HALI)." (PMID 37938537, 2024). "Specifically, Rd regulates autophagy through the AMPK/mTOR/ULK1 signaling pathway, both in TAA-induced acute liver injury in vivo and LPS-induced HSC-T6 cells in vitro." (PMID 39875579, 2025). "Some studies have suggested that multiple signal transduction pathways, such as mammalian target of rapamycin (mTOR), nuclear factor kappa-B (NF-κB), Mixed Lineage Kinase Domain-Like (MLKL), etc., play a role in alcohol-induced brain injury." (PMID 37240148, 2023). "Therefore, selective inhibition of SIRT1 by EX-527 might improve endotoxemia-related acute lung injury moderately via inhibition of mTOR, which suggests that selective SIRT1 inhibitors may have potential for the pharmacological treatment of inflammatory lung injury." (PMID 32365537, 2020). "We measured total and phosphorylated protein levels of mTOR and its downstream effectors, P70S6K and 4E-BP1, in the ACC 1, 4, 7, and 14 days after nerve injury (POD 1, POD 4, POD 7, and POD 14) as well as in normal and sham injury groups." (PMID 30032425, 2019). "While previous studies have shown the nephroprotective effects of statins, including pitavastatin, the specific involvement of the miR-93/PTEN/Akt/mTOR pathway in mediating these effects has not been elucidated in vivo in the context of xenobiotic-induced kidney injury." (PMID 38293706, 2024).
lymph node metastasis (30 papers, 2009 to 2025). "Elevated levels of mTOR and related signaling molecules were associated with larger tumor sizes, lymph node metastasis, and more advanced TNM stages." (PMID 40754657, 2025). "Meanwhile, p-mTOR overexpression was tightly associated with differentiation, depth of invasion, lymph node metastasis, TNM stage and OS (P < 0.05)." (PMID 29233126, 2017). "MTOR showed a trend of association with lymph node metastasis (OR = 1.72, 95%CI 0.98–3.01, P = 0.06) and late TNM stage (OR = 3.13, 95%CI 0.72–13.61, P = 0.13)." (PMID 29233126, 2017). "Meanwhile, in the present study, p-mTOR was significantly linked to differentiation (P < 0.01), depth of invasion (P < 0.01), lymph node metastasis (P = 0.04) and TNM stage (P = 0.02)." (PMID 28005970, 2016). "Expression of p-mTOR was significantly associated with differentiation (P < 0.01), depth of invasion (P < 0.01), lymph node metastasis (P = 0.04) and TNM stage (P = 0.02)." (PMID 28005970, 2016). "What is more, our results suggested that there was a consistent trend that mTOR overexpression rate was associated with the status of lymph node metastasis, the pathological differentiation, and the rise of clinical stage." (PMID 26357655, 2015). "We also analyzed the relationship between mTOR genetic polymorphisms and clinicopathological characteristics, including tumor size, lymph node metastasis, and the statuses of estrogen receptor (ER), progesterone receptor (PR), and human epidermal growth factor receptor type-2 (Her-2)." (PMID 27533457, 2016). "In conclusion, mTOR and c‐Myc are important for lymphangiogenesis of pNET and are potential therapeutic targets for prevention and treatment of lymph node metastasis in pNET." (PMID 33128283, 2021). "Activation of mTOR pathway was shown to be associated with increased LVD and lymph node metastasis via upregulation of VEGFC in various cancers in in vitro and in vivo models and in human samples." (PMID 33128283, 2021). "Most importantly, NSCLC patients with lymph node metastasis had significantly elevated expression of p-Akt, p-mTOR and p-eIF4E (all P<0.05)." (PMID 32023262, 2020). "Further study indicated that HUMT exerted its function by recruiting YBX1 protein to the promoter region of FOXK1 and promoted its transcription, activating lymph node metastasis-related Akt/mTOR/VEGFC signaling." (PMID 32138762, 2020). "Meanwhile, p-mTOR was significantly associated with age, tumor location, depth of invasion, and TNM stage (all P < 0.05), with a trend of higher risk of lymph node metastasis." (PMID 29233126, 2017). "It should be noted that p-mTOR overexpression showed a trend of increasing lymph node metastasis (OR = 1.57, 95%CI 0.83–2.98, P = 0.17)." (PMID 29233126, 2017). "In our series, 23% of predominantly pleomorphic tumours contained increased mTOR, and these patients had lymph-node metastasis." (PMID 22454081, 2012). "A significant correlation was found between high p-mTOR expression and lymph node metastasis (p = 0.004) and recurrence (p = 0.021)." (PMID 20338061, 2010). "Moreover, reduced PTEN expression correlates with an advanced stage, larger tumor size, and lymph node metastasis, while increased AKT/mTOR expression is associated with a worse prognosis." (PMID 40647429, 2025). "The result suggests that mTOR plays an important role for lymph node metastasis in pNET." (PMID 33128283, 2021). "Case 1 showed lymph node metastasis, and received mTOR inhibitors." (PMID 29901594, 2018). "The expression level of PTEN, mTOR, p-mTOR, and S6K1 was closely related to the presence of lymph node metastases." (PMID 33572326, 2021). "In particular, our findings suggest that rNEN-L patients diagnosed with lymph node metastases may be more sensitive to RET inhibitors (sorafenib, vandetinib) as well as PI3K/AKT/MTOR and JAK inhibitors." (PMID 39548061, 2024).
lymph node metastasis (continued). "PI3K/AKT/mTOR protein pathway signaling in patients with lymph node metastasis (n = 6), did not reveal common, complete pathway up or down modulation for all 6 patients." (PMID 37491309, 2023). "The p-mTOR overexpression was independent of sex, age, differentiation, lymph node metastasis, and distant metastasis suggesting that p-mTOR was involved in tumor progression." (PMID 28005970, 2016). "The expression of mTOR was not related to the histologic type, the depth of infiltration, and lymph node metastasis (all P > 0.05) but closely related to the TNM stage (P < 0.01)." (PMID 24818169, 2014). "mTOR expression was inversely correlated with tumour size, depth of invasion, lymphatic invasion, lymph node metastasis and UICC staging (p < 0.05), but not with sex or venous invasion (p > 0.05)." (PMID 20003385, 2009). "HER-2 overexpression and activated excessive signaling triggered by pathways including phosphoinositide 3 kinase/Akt/mammalian target of rapamycin (Akt/PI3K/mTOR) may lead to more malignant clinical behaviors, including lymph node metastasis, local invasion, and high recurrence rate." (PMID 39045556, 2024). "Moreover, it was stated that the expression level of the PIK3CA, PIK3R1, PTEN, AKT1, mTOR genes does not depend on the patients’ age, lymph node metastases, ER, PR status and Ki-67 index." (PMID 33669698, 2021). "Most importantly, positive expression of p-Akt, p-mTOR and p-eIF4E in NSCLC patients with lymph node metastasis (LNM) was significantly higher than those without LNM (P = 0.033, P = 0.025 and P = 0.036, respectively)." (PMID 32023262, 2020).